ACSS2 (acyl-CoA synthetase short chain family member 2)
Diseases named in the same sentence as ACSS2 in open-access papers (continued):
Sharing a sentence is not in itself a finding about the gene and the disease.
lung carcinoma (8 papers, 2018 to 2025). "The expression levels of lipid metabolism-related enzymes, such as fatty acid synthase (FASN), acetyl-CoA carboxylase (ACC), and acetyl-CoA synthetase (ACSS2), are frequently elevated in lung cancer." (PMID 40657374, 2025). "Lung cancer is characterized by an increased expression of acetyl-CoA synthetase 2 (ACSS2), which catalyzes the ATP-dependent ligation of acetate and CoA to produce acetyl-CoA." (PMID 38731909, 2024). "MTB-9655, the first oral inhibitor of ACSS2, was shown to have anti-tumor effect in xenograft mouse model of ACSS2-high lung cancer." (PMID 37296863, 2023). "This research discovered a unique method of miR-15a-5p in preventing lung cancer cell progression via reducing lipid metabolism via regulation of ACSS2-mediated acetyl-CoA activities and histone acetylation." (PMID 36483029, 2022). "MiR-15a-5p inhibits acetate uptake and acyl-CoA synthetase short chain family member 2 (ACSS2) and H4 acetylation in the nucleus under hypoxia, inhibiting fatty acid synthesis in lung cancer cells and further suppressing malignancy in lung cancer." (PMID 35004688, 2021).
renal cell carcinoma (8 papers, 2019 to 2025). "The high expression of ACSS2 in renal cell carcinoma promotes the expression of lysosome-associated membrane protein 1 (LAMP1) to promote tumor proliferation and invasion." (PMID 35740562, 2022). "Initially, ACSS2 expression in renal cell carcinoma tissues was found to be markedly higher than that in adjacent tissues, and this increased expression was positively related to tumor metastasis." (PMID 35798917, 2022). "In renal cell carcinoma, ACSS2 knockdown inhibited growth, migration, and invasion, whereas overexpression of ACSS2 enhanced these effects, implying that ACSS2 increases renal cell tumor aggressiveness." (PMID 33304273, 2020). "In the present study, we first measured the effect of acetate on zinc finger transcriptional repressor SNAI1 and acetyl-CoA synthetase 2 (ACSS2) under glucose limitation in renal cell carcinoma cell lines, 786-O and ACHN." (PMID 32458971, 2020). "Recently, it has been found that acetyl-CoA synthetase 2 (ACSS2) is related to the metastasis of renal cell carcinoma (RCC)." (PMID 32458971, 2020). "Moreover, ACSS2 is upregulated in renal cell carcinoma and promotes migration and invasion of renal cancer cells." (PMID 38263056, 2024). "ACSS2 showed no influence on the proliferation and apoptosis of tumor cells, but reduced ACSS2 expression inhibited lysosome-associated membrane protein 1 (LAMP1) protein expression compared with that in the control group, thus preventing the migration and invasion of renal cell carcinoma cells." (PMID 35798917, 2022). "Under glucose limitation, acetate activates ACSS2 to mediate SNA1 histone acetylation, a key EMT (epithelial to mesenchymal transition) driver, thereby promoting renal cell carcinoma metastasis." (PMID 40863614, 2025). "The knockdown of ACSS2 reduces not only LAMP1 mRNA levels but also LAMP1 protein levels, which in turn leads to the invasion and metastasis of renal cell carcinomas." (PMID 35740562, 2022).
brain tumors (7 papers, 2021 to 2025). "In their study of primary and metastatic mouse orthotopic brain tumours, Mashimo and co-workers demonstrate that lesions in the brain have the capacity to oxidise acetate simultaneously with glucose; and associated acetate oxidation with expression of ACSS2 and prognosis." (PMID 39915301, 2025). "A 2025 study reported that the mitochondrial alanyl-tRNA synthetase ACSS2 functions as a lactyl-CoA synthetase in brain tumors." (PMID 41463052, 2025). "KAT2A has been shown to interact with ACSS2 to promote brain tumor growth and immune evasion." (PMID 41225436, 2025). "Thus, we sought to identify novel ACSS2 inhibitor chemotypes with BBB permeability in order to target brain tumors." (PMID 38818373, 2024). "We show that in BCBM cells targeting ACSS2 reduces levels of FASN levels thus suggesting that ACSS2 may be an attractive alternative therapeutic strategy for the treatment of lipid-dependent brain tumors." (PMID 38818373, 2024). "Importantly, genetically targeting ACSS2 in brain tumors has previously been shown to block tumorigenesis." (PMID 38818373, 2024). "FPIA is a monocarboxylate; in studies by Mashimo, it was posited that the monocarboxylate, acetate, is used by primary brain tumours and IMD alike for growth in preference to glucose, and that the enzyme ACSS2, might be responsible for the adaption of cancers to grow in this niche." (PMID 39915301, 2025).
liver cancer (7 papers, 2017 to 2024). An epithelial or non-epithelial malignant neoplasm that arises from the liver. "In liver cancer cells, acetate-induced lipogenesis is regulated by ACSS2 and ACSS1 and is associated with regulation of FASN expression." (PMID 38818373, 2024). "Loss of ACSS2 suppresses tumor development in certain mouse liver cancer models, including c-Myc expression combined with PTEN knockout in the liver (Alb-c-Myc; Alb-Cre; Ptenlox/lox)." (PMID 32947972, 2020). "Notably, ACSS2 downregulation in liver cancer cells was associated with increased tumor occurrence in vivo." (PMID 38528124, 2024). "ACSS2 levels are generally high in normal human liver tissues, and it has been noted that ACSS2 is maintained in high-ACSS2 liver cancer cells but is lost in low-ACSS2 cancer cells." (PMID 38528124, 2024). "Liver cancer patients with high amounts of Acetyl-CoA synthetase 2 (ACSS2), an enzyme that helps break down acetate, tend to have a better outlook than those with low amounts, according to a study by Kyung Hee Jung and team." (PMID 38528124, 2024). "Taken together, these data show that ACSS2 is involved in anabolic lipid metabolism in high-ACSS2 liver cancer cells and that the inhibition of ACSS2 can increase glycolysis." (PMID 38528124, 2024). "The ACSS2-malignancy relationship was further tested in a larger cohort of liver cancer patients derived from TCGA." (PMID 38528124, 2024). "Overall, these findings confirm the link between lower ACSS2 expression and more severe malignancy in liver cancer patients." (PMID 38528124, 2024). "Consistent results were also obtained in a DEN-induced rat liver cancer model, in which ACSS2 expression decreased as the tumor developed." (PMID 38528124, 2024). "Targeting ACSS2 and acetate metabolism would be a highly interesting concept for treating liver cancer." (PMID 32947972, 2020). "Indeed, our cell, animal, and patient results consistently showed that high acetate uptake/ACSS2 expression can occur in glucose- or nutrient-replete conditions in lower-grade liver cancer cells or in tumors that feature reduced hypoxia." (PMID 38528124, 2024). "Clinically, we initially found that ACSS2 expression was decreased in liver cancer patients." (PMID 38528124, 2024). "The results suggest that ACSS2 could be a potential indicator for liver cancer outlook and could assist in making treatment choices." (PMID 38528124, 2024). "Overall, acetate uptake under normal physiological conditions seems to be an inherent property of liver tissue, and there is heterogeneity in acetate uptake among liver cancer cells based on the expression of ACSS2, which in turn affects liver cancer cell growth." (PMID 38528124, 2024). "First, PET-CT-detectable metabotypes of ACSS2-driven acetate uptake may be noninvasive biomarkers for lower-malignancy liver cancers." (PMID 38528124, 2024). "Acetate uptake correlates with ACSS2 expression in the HCC of liver cancer models." (PMID 32947972, 2020). "The critical acetate oxidation enzyme in cancer appears to be the acetyl-CoA synthetase enzyme ACSS2, which was found to be essential for tumorigenesis in a MYC-driven model of liver cancer, and increased expression of ACSS2 was associated with poor prognosis in TNBC." (PMID 28443280, 2017). "However, the nutrient usage and metabolic characteristics of the liver differ from those of other organs; therefore, the mechanism of ACSS2-mediated acetate metabolism may also differ in liver cancer." (PMID 38528124, 2024). "In addition, ACSS2 was shown to reduce tumor burden in a liver cancer model." (PMID 35798917, 2022). "Based on our results and the established roles of ACSS2 in acetate usage, ACSS2-driven high acetate uptake seems to be an inherent property of a normal liver that may be only slightly lost (if at all) in low-malignancy liver cancer but largely lost in high-malignancy liver cancer." (PMID 38528124, 2024).
liver cancer (continued). "We demonstrated that acetate uptake by ACSS2 in liver cancer is independent of glucose depletion and contributes to lipid anabolic metabolism and reduced malignancy, thereby leading to a better prognosis for liver cancer patients." (PMID 38528124, 2024). "Among liver cancer cells, those with high ACSS2 expression avidly absorbed acetate even in a glucose-sufficient environment, whereas those with low ACSS2 expression did not, thereby showing correlations with their respective ACSS2 expression." (PMID 38528124, 2024).
gastric cancer (6 papers, 2019 to 2024). A primary or metastatic malignant neoplasm involving the stomach. "Surprisingly, loss of ACSS2 expression was identified in a high proportion of gastric cancers (62.6%), whereas this was more commonly observed in poorly differentiated gastric adenocarcinoma or signet ring cell carcinoma." (PMID 35785165, 2022). "In clinical practice, the deficiency of ACSS2 expression could serve as an independent prognostic factor predicting poorer prognosis in patients with gastric cancer, which was found to be especially correlated with Microsatellite Instability (MSI)." (PMID 35785165, 2022). "Loss of genes, such as INSIG1 and ACSS2, is responsible for the advancement of gastric cancer, but inactivation of these genes may be linked with the development of BRCA." (PMID 31311202, 2019). "This phenomenon is particularly relevant in cancers exhibiting microsatellite instability (MSI), such as MSI-high gastric cancers and CRCs; however, no clinical data have yet established a direct relationship among ACSS2, MSI-high tumors, and Sox2 expression." (PMID 38473392, 2024). "In gastric cancer and CRC, unlike other types of cancer, lower expression of ACSS2 is associated with tumor progression and metastasis." (PMID 38473392, 2024).
colon carcinoma (5 papers, 2017 to 2025). "Acss2 has also been implicated in colon cancer growth, although the studies are more limited compared with HIF and colon cancer." (PMID 36862715, 2023). "We find that Acss2/HIF-2 signaling is activated by oxygen or glucose deprivation in two human colon cancer-derived cell lines, HCT116 and HT29, and is crucial for colony formation, migration, and invasion in cell culture studies." (PMID 36862715, 2023). "Another finding from the Acss2 immunohistochemical analyses was the predominantly diffuse pattern of Acss2 in the cytosol of benign tissue versus a more localized pattern in the cytosol of colon cancer samples." (PMID 36862715, 2023). "In this report, we assess the role of Acss2/HIF-2 signaling in colon cancer using cell, mouse, and human colon cancer studies." (PMID 36862715, 2023). "Acss2 immunoreactivity was detected in most human colon cancer samples that we examined and was preferentially nuclear." (PMID 36862715, 2023). "For slides, Acss2 immunoreactivity in the cytosol of benign tissues was scored more often as predominantly diffuse whereas Acss2 immunoreactivity in the cytosol of colon cancer samples was more often scored as localized." (PMID 36862715, 2023). "The immunohistochemical analyses of Acss2 in human colon cancer samples and their benign neighboring tissue is noteworthy in several respects." (PMID 36862715, 2023). "Knockdown of Acss2 in several colon cancer cell lines enhanced cell death under hypoxia and slowed tumor growth in mice, which was attributed to decreased Acss2-dependent cytosolic acetate uptake and lipid incorporation in tumor cells." (PMID 36862715, 2023). "Finally, Acss2 in human colon cancer samples is most frequently localized in the nucleus, consistent with it having a signaling role." (PMID 36862715, 2023). "Acss2 immunoreactivity is enriched in the nucleus of colon cancer cells." (PMID 36862715, 2023). "Indeed, acetate supplementation promotes in vitro migration and invasion of HCT116 and HT29 colon cancer cells, which is blunted with inhibition of Acss2 or HIF-2 signaling." (PMID 36862715, 2023). "The similar and favorable outcomes for mice with HCT116 and HT29 derived flank tumors marked by impaired Acss2/HIF-2 signaling suggest that targeting this pathway may have broad efficacy in colon cancer." (PMID 36862715, 2023). "Based on these data, inhibition of Acss2 or HIF-2 as a monotherapy may be advantageous in colon cancer therapies." (PMID 36862715, 2023). "To evaluate whether HIF-2 stress signaling is regulated by Acss2 in colon cancer derived cell lines, we first asked whether HIF-1α and HIF-2α were present in HCT116 and HT29 cell lines and whether their levels were affected by oxygen or glucose deprivation." (PMID 36862715, 2023). "Finally, we examine the pattern as well as presence of Acss2 immunoreactivity in the cytosol and nucleus of human colon cancer samples compared to benign tissue obtained from the same patient." (PMID 36862715, 2023). "Although some heterogenous staining may be artifactual, it is possible that Acss2 steady-state protein levels vary in different anatomical portions of the colon cancer solid tumor." (PMID 36862715, 2023). "The effect of the solid tumor microenvironment, combined with its anatomical location that results in exposure to high acetate levels generated by the gut microbiome, may explain why Acss2 protein localization in colon cancer samples is preferentially nuclear." (PMID 36862715, 2023). "In this study, we examine the role of Acss2/HIF-2 signaling in colon cancer." (PMID 36862715, 2023). "We assess whether colony formation, migration, and invasion of HCT116 and HT29 colon cancer cell lines are regulated by Acss2/HIF-2 signaling." (PMID 36862715, 2023). "Acss2 immunoreactivity exhibits distinct patterns in colon cancer cells." (PMID 36862715, 2023). "Targeted inhibition of Acss2/HIF-2 signaling may have synergistic effects for some colon cancer patients." (PMID 36862715, 2023).
colon carcinoma (continued). "We examine molecular features of Acss2/HIF-2 signaling in HCT116 and HT29 colon cancer cells exposed to oxygen or glucose deprivation." (PMID 36862715, 2023). "Moreover, the effect of impeding Acss2/HIF-2 signaling on growth and metastasis of HCT116 and HT29 derived colon cancer flank tumors in the current study is impressive." (PMID 36862715, 2023). "Moreover, because of their positions in the same signaling axis, targeting both Acss2 and HIF-2 may be a particularly attractive treatment strategy for colon cancer patients with more advanced disease." (PMID 36862715, 2023). "However, some human colon cancer samples in our study had no or minimal Acss2 immunoreactivity in either the cytosol or nucleus." (PMID 36862715, 2023). "However, the pattern of cytosolic Acss2 being predominantly diffuse in benign tissue samples, versus localized and not diffuse when present in colon cancer samples, was evident by the increased diffuse/localized ratio for cytosolic reads of benign tissue for both slide and select image samples." (PMID 36862715, 2023).
colorectal cancer (5 papers, 2020 to 2024). A primary or metastatic malignant neoplasm that affects the colon or rectum. "To investigate the relationship between ACSS2 expression and intracellular cholesterol levels in colorectal cancer, we measured cholesterol ester levels in KRAS mutant mouse colon epithelial cells." (PMID 38464238, 2024). "Downregulation of ACSS2 expression is a metabolic marker of tumor progression and aggressive behavior in colorectal cancer." (PMID 35798917, 2022). "Decreased ACSS2 expression in colorectal cancer is strongly related to advanced tumor–node–metastasis (TNM) stage, poor differentiation, and cancer recurrence, and is an independent prognostic factor for poor 5-year progression-free survival." (PMID 35798917, 2022). "In colorectal cancer, the significance of ACSS2 expression may be different from that in other malignancies, since normal colon cells utilize short-chain fatty acids as a fuel source, unlike the mechanism of ACSS2, which utilizes acetic acid as a carbon source for tumor cells." (PMID 35798917, 2022).
prostate carcinoma (5 papers, 2018 to 2022). A carcinoma that arises from epithelial cells of the prostate gland. "In fact, the enzyme nucleocytosol-localised acetyl CoA synthetase (ACSS2) involved in fatty acid biosynthesis is implicated as crucial enzyme for growth and survival of breast and prostate cancer cells cultured in hypoxic and low nutrient environment." (PMID 30531924, 2018). "Indeed, recent reports show that the expression of both ACLY and ACSS2 is increased at protein levels in prostate cancer tissue." (PMID 36497382, 2022). "Moreover, a correlation between breast and prostate cancer with acetate metabolism and ACSS-2 activity has been identified." (PMID 36578540, 2022). "The expression level of ACSS2 was correlated with the invasion degree of prostate cancer." (PMID 35740562, 2022).
cervical squamous cell carcinoma (4 papers, 2022 to 2025). A squamous cell carcinoma arising from the cervical epithelium. "Immunohistochemistry of tumor tissues and adjacent normal tissues collected from 240 patients with cervical squamous cell carcinomas revealed that the expression of ACSS2 was significantly higher than that of adjacent normal tissues." (PMID 35740562, 2022). "An analysis of the relationship between ACSS2 expression and immune cell-derived cytokines in cervical squamous cell carcinoma (CESC) using the TIMR database revealed that ACSS2 was significantly associated with the gene expression of immunosuppressive factors in CESC." (PMID 35740562, 2022). "In cervical squamous cell carcinoma (CESC), ACSS2 upregulation fosters an immunosuppressive TIME by enhancing cancer-associated fibroblast (CAF) exhaustion and Treg activity, promoting tumor invasion and metastasis." (PMID 41029427, 2025). "In cervical squamous cell carcinoma (CESC), ACSS2 expression is associated with infiltration of B cells, CD4+ and CD8+ T cells, and cancer-associated fibroblasts (CAFs), and high ACSS2 expression is associated with shorter overall survival times." (PMID 35798917, 2022).
fatty liver disease (4 papers, 2021 to 2025). A reversible condition wherein large vacuoles of triglyceride fat accumulate in liver cells via the process of steatosis. "Mice with a liver specific deletion of PTEN have increased levels of ACLY and ACSS2, and they develop fatty liver disease by early adulthood." (PMID 40636718, 2025). "Recent studies have shown that inhibiting SREBP1, ACLY, ACSS2, ACACA, and FASN can improve fatty liver disease." (PMID 37065701, 2023). "In diet-induced obese mice, lack of ACSS2 results in a significant reduction in body weight and hepatic steatosis." (PMID 33853536, 2021).